LPAR4 (lysophosphatidic acid receptor 4)
Description:
Receptor for lysophosphatidic acid (LPA), a mediator of diverse cellular activities. Transduces a signal by increasing the intracellular calcium ions and by stimulating adenylyl cyclase activity. The rank order of potency for agonists of this receptor is 1-oleoyl- > 1-stearoyl- > 1-palmitoyl- > 1-myristoyl- > 1-alkyl- > 1-alkenyl-LPA.
Synonyms: P2Y9; GPR23; LPA4; P2RY9; P2Y5-LIKE
Tractability: Small molecule: a high-quality ligand is known; it belongs to a druggable protein family. Antibody: its Gene Ontology location is reachable by antibodies, with high confidence; UniProt places it where antibodies can reach, with medium confidence; UniProt predicts a signal peptide or a membrane-spanning region; the Human Protein Atlas places it where antibodies can reach. PROTAC: a small molecule that binds it is known.
Target class: EDG receptor; Family A G protein-coupled receptor; Lipid-like ligand receptor (family A GPCR); Membrane receptor; Small molecule receptor (family A GPCR)
Gene: Protein-coding gene on chromosome X (78,747,680 to 78,758,724, forward strand). Ensembl gene ENSG00000147145.
Subcellular location: Cell membrane
Subcellular location (Human Protein Atlas): Plasma membrane; Nuclear bodies; Vesicles
Pathways (Reactome):
Signal Transduction: G alpha (q) signalling events; P2Y receptors
Gene Ontology:
Molecular function: protein binding; lysophosphatidic acid receptor activity; G protein-coupled receptor activity; lysophosphatidic acid binding
Biological process: G protein-coupled receptor signaling pathway
Cellular component: plasma membrane; membrane
Homologues: Orthologues: chimpanzee LPAR4 (99% identical), macaque LPAR4 (99% identical), mouse Lpar4 (98% identical), rat Lpar4 (98% identical), dog LPAR4 (97% identical), pig LPAR4 (97% identical), tropical clawed frog lpar4 (75% identical), zebrafish lpar4 (61% identical). Paralogues in human: LPAR6 (49% identical), P2RY8 (26% identical), P2RY10 (26% identical), CYSLTR1 (25% identical), GPR17 (25% identical), GPR35 (25% identical), CYSLTR2 (25% identical), GPR65 (24% identical), F2R (23% identical), GPR55 (23% identical), GPR18 (23% identical), GPR4 (23% identical), and 4 more.
Diseases named in the same sentence as LPAR4 in open-access papers:
LPAR4 is named in the same sentence as 46 diseases in open-access papers, as found by Europe PMC text mining. Sharing a sentence is not in itself a finding about the gene and the disease. The quoted sentences say what the papers report.
pancreatic cancer (4 papers, 2021 to 2024). "In addition to our finding that PCa patients in the high LPAR5 expression group had worse survival, other LPAR subtypes were associated with poor survival such as LPAR1 in melanoma, LPAR2 in adrenocortical carcinoma, LPAR3 in pancreatic cancer, and LPAR4 in renal papillary carcinoma." (PMID 36806315, 2023). "For example, LPAR5 is mainly expressed in stomach, colon and pancreatic cancer, while LPAR3 and LPAR4 are predominantly expressed in pancreatic cancer." (PMID 37550785, 2023). "Reversely, proliferation and/or motility of cancer cells also showed a decrease after LPA signalling through LPAR2 in melanoma, LPAR4 in pancreatic, colon, and head and neck cancer, LPAR5 in pancreatic cancer and melanoma, and LPAR6 in colon cancer." (PMID 34722305, 2021). "Proliferation and/or motility of cancer cells were promoted after LPA signalling through the LPAR1 in colon, gastric, and breast cancer, LPAR2 in colon and renal cancer, LPAR3 in colon, pancreatic, and breast cancer, LPAR4 in fibrosarcoma, and LPAR6 in hepatic and pancreatic cancer." (PMID 34722305, 2021).
atherosclerosis (2 papers, 2022 to 2023). A disease characterized by the build-up of fatty material and calcium deposition in the arterial wall resulting in partial or complete occlusion of the arterial lumen. "LPAR4 inhibition has been demonstrated to decrease the experimental atherosclerosis elicited by adeno-associated virus expressing gain-of-function allele of the PCSK9 D377Y mutation in rats fed a fat-rich diet." (PMID 35269385, 2022).
colon cancer (2 papers, 2017 to 2019). "LPAR4 mutations have previously been reported in 16% (1/6) only in human colon cancer cell lines and recently in PTCs." (PMID 31289610, 2019).
COVID-19 (2 papers, 2021 to 2025). A disease caused by infection with severe acute respiratory syndrome coronavirus 2. "The proximity score of promethazine was significantly low partly by targeting genes including CALM1, KCNS1, LPAR4, LPAR6, P2RY12, P2PY8, and P2RX5, which were DEGs between T cell subsets of COVID-19 samples and healthy controls." (PMID 33919660, 2021).
glioma (2 papers, 2012 to 2022). A benign or malignant brain and spinal cord tumor that arises from glial cells (astrocytes, oligodendrocytes, ependymal cells). "Interestingly, among the genes that we found to be up-regulated in the HD-type, a few like GRIA2, BCAN and LPAR4 were already shown to be directly or indirectly implicated with glioma cell invasion." (PMID 22901239, 2012).
Hypertension (2 papers, 2019 to 2024). The presence of chronic increased pressure in the systemic arterial system. "Although unsaturated LPAs evoke hypertension more efficiently than saturated LPAs, which is in agreement with our findings, this hypertensive response is mediated primarily by LPAR4 and LPAR6." (PMID 38999980, 2024).
myocardial infarction (2 papers, 2021 to 2023). Gross necrosis of the myocardium, as a result of interruption of the blood supply to the area, as in coronary thrombosis. "In an adult bone marrow transplantation model using LPAR4 promoter-driven GFP cells, we observed two LPAR4+ cell types in the heart following myocardial infarction (MI)." (PMID 37394586, 2023). "Besides, we used a mouse myocardial infarction (MI) model to highlight the concept of cell-free regeneration therapy with the optimal protocol to modulate the signaling of LPAR4." (PMID 33160074, 2021). "Modulation of LPAR4-positive cells may be a promising strategy for repairing myocardium after myocardial infarction." (PMID 33160074, 2021).
prostate carcinoma (2 papers, 2019 to 2023). A carcinoma that arises from epithelial cells of the prostate gland. "A high rate of 50% (1/2) LPAR4 mutations was found in prostate cancer cell line but only two cell lines were reported." (PMID 31289610, 2019).
asthma (1 paper, 2022). "The downregulated genes in the LPAR4 low-expression group showed a strong correlation with allograft rejection, asthma, autoimmune thyroid disease, phototransduction, and ribosome pathways." (PMID 36465614, 2022). "Furthermore, the enriched pathways of NRAD1 and LPAR4 included immune system pathways, such as those related to complement and coagulation cascades, asthma, and autoimmune thyroid disease." (PMID 36465614, 2022).
differentiated thyroid carcinoma (1 paper, 2019). Differentiated thyroid carcinoma (DTC), also known as papillary or follicular thyroid carcinoma, is a slow-growing malignancy usually presenting in adults as an asymptomatic thyroid mass. "The study found LPAR4 mutations as novel gene mutations in adult population with differentiated thyroid cancer (DTC)." (PMID 31289610, 2019).
hyperlipidemia (1 paper, 2022). "For these experiments, LPAR4 deficient mice (LPAR4Y/−) or WT controls were treated with PCSK9D377Y.AAV and fed Western diet to elicit hyperlipidemia." (PMID 35383201, 2022).
infarction (1 paper, 2021). A localised pathological necrosis of tissue resulting from obstruction of the blood supply usually by a thrombus, an embolus, or vascular torsion. "Based on these in vivo data, we confirmed that the protocol of sequential stimulating and then inhibition of LPAR4 signaling not only markedly increased CMC differentiation from ESC/iPSC but also boosted up post-infarction myocardial repair." (PMID 33160074, 2021). "We applied the established protocol of sequential stimulation and inhibition of LPAR4 signaling to repair the myocardium after infarction in mice." (PMID 33160074, 2021).
lung carcinoma (1 paper, 2020). "Next, we determined the expression levels of P2X sub-families P2RX1–7 and P2Y receptors P2RY1, P2RY2, P2RY4, P2RY5 (LPAR6), P2RY6, P2RY7 (LTB4R), P2RY8, P2RY9 (LPAR4), P2RY10–14 in normal lung tissues and lung cancer tissues." (PMID 32638267, 2020).
papillary thyroid cancers (1 paper, 2019). "Whole exome sequencing (WES) recently identified frequent mutations in the genes of GPCR-mediated PI3K pathway (LPAR4, PIK3CA, and PTEN) in a Chinese population with papillary thyroid cancers (PTCs)." (PMID 31289610, 2019).
preeclampsia (1 paper, 2022). Preeclampsia is a hypertensive disorder of pregnancy that is characterized by new-onset hypertension with proteinuria presenting after 20 weeks of gestation, and depending on mild or severe forms may initially present with severe headache, visual disturbances, and hyperreflexia. "Some genes are noted to play key roles in preeclampsia, including LPAR4/5, CRLR, NPY, TACR1/2, and SFRP4/5, whose functions generally relate to angiogenesis and vasodilation or vasoconstriction." (PMID 35269385, 2022).
thyroid cancer (1 paper, 2019). "Here, we studied mutations in the major genes (LPAR4, PIK3CA, and PTEN) of the GPCR-mediated PI3K pathway in a large series of pediatric and adult DTCs, and in aggressive thyroid cancer (PDTC and ATC) samples (n = 323) from a Saudi Arab population." (PMID 31289610, 2019). "Each PIK3CA and PTEN genes harbored somatic mutations in 7% (8/117) of aggressive thyroid cancers (PDTCs and ATCs) while no mutation was found in LPAR4 gene." (PMID 31289610, 2019). "We also found no mutation in the LPAR4, PIK3CA and PTEN genes of the 13 cases of PDTCs and ATCs (aggressive thyroid cancers)." (PMID 31289610, 2019). "LPAR4 mutations were not studied in pure pediatric and adult DTC groups, and aggressive thyroid cancers (PDTC and ATC)." (PMID 31289610, 2019).
cancer (14 papers, 2014 to 2025). A tumor composed of atypical neoplastic, often pleomorphic cells that invade other tissues. "LPAR1 and LPAR4 expression levels were highest in cancer-associated fibroblasts (CAFs), while most of the LPAR6 expression determined was in endothelial cells followed by myeloid cells and CAFs." (PMID 37372960, 2023). "LPAR4 mutations in pan-tumors (0.8%) were comparable to that of DTCs though pan-cancer cell lines had a slightly higher prevalence (3.3%)." (PMID 31289610, 2019). "Finally, module 4 included the genes PLCB4, MMP1, CTNNB1, EGF, F2R, and LPAR4, associated with pathways in cancer, Rap1 signalling pathway, and phospholipase D signalling pathways." (PMID 31178673, 2019). "Specifically, for GBM (adults) and GBM_DE (children), four genes (CASP8, PIK3CA, PTEN, LPAR4) related to pathways in cancer are identified." (PMID 40768543, 2025). "LPAR1 and LPAR4 were highest in cancer-associated fibroblasts, while LPAR6 was highest in endothelial cells, and LPAR2 was highest in cancer epithelial cells." (PMID 37372960, 2023). "These suggested the involvement of LPAR4 in YAP-mediated cancer progression." (PMID 34209775, 2021). "LPAR4 (P2Y9/GPR23) and LPAR5 (GPR92) in cancer cells demonstrate inhibitory effects on proliferation and migration/invasion, which is in contrast to the effects of LPAR1–3." (PMID 32887262, 2020). "We, therefore, analyzed LPAR4, PIK3CA and PTEN genes in TCGA data of pan-cancer cell lines and tumors." (PMID 31289610, 2019). "As mentioned in the results section, PLD network involves proteins such as LPAR4, LPAR6, HCRTR1, and GRM5, as well as pathways like EGF/EGFR SP, which their roles have been proven in initiation and progression of several cancers." (PMID 29062084, 2017). "In contrast to LPAR1–3, LPAR4 and LPAR5 negatively affected cancer cell proliferation and motility." (PMID 34209775, 2021). "For the non-EDG LPA-receptors, LPAR4-6, information on their role in cancer is very limited and few studies exist." (PMID 24928086, 2014). "However, LPAR4 vs PIK3CA and LPAR4 vs PTEN were not related in either mutually exclusive or a co-occurring manner (p = 0.805 and p = 0.788, respectively) in pan-cancer cell lines." (PMID 31289610, 2019).
tumor (12 papers, 2019 to 2025). "While tumor-promoting activities are more consistently associated with LPAR1–3, which are all coupled to the Gi/Ras/MAPK pathway, LPAR4–6 predominantly show anti-tumor activities." (PMID 31658655, 2019). "LPAR4 attenuates tumor motility and colony formation in colon cancer cell lines." (PMID 34209775, 2021). "Similarly, LPAR4 depletion increases tumor motility in pancreatic cancer cells and increases tumor proliferation in head and neck carcinoma." (PMID 34209775, 2021). "Inflammatory signaling pathways were elevated, particularly in high-LPAR6-expressing tumors in all cohorts, and in tumor suppressor pathways apart from DNA repair pathways in high-LPAR1-, LPAR4-, and LPAR6-expressing tumors." (PMID 37372960, 2023). "Moreover, LPAR4 and PTEN could co-occur in pan-tumor samples (p = 0.003)." (PMID 31289610, 2019). "On the other hand, the inhibition of LPAR4 and LPAR5 could not have a beneficial effect due to their inhibitory activities on tumor cell growth and motility." (PMID 39062979, 2024).
LPAR4 also shares sentences with these, for which no sentence is quoted: breast carcinoma (3 papers); melanoma (3); Obesity (3); fibrosarcoma (2); Insulin resistance (2); neuroblastoma (2); adenomyosis (1); adrenocortical carcinoma (1); anaplastic thyroid cancer (1); aneurysm (1); autism (1); autoimmune thyroid disease (1); bladder cancer (1); brain tumors (1); cavernous hemangioma (1); colitis (1); colorectal cancer (1); endometriosis (1); head and neck squamous cell carcinoma (1); infection (1); interstitial cystitis (1); ischemic stroke (1); metabolic disease (1); metabolic syndrome (1); multinodular goiter (1); prostatitis (1); squamous cell carcinoma (1); steatosis (1).